CXCR4 (C-X-C motif chemokine receptor 4)
Diseases named in the same sentence as CXCR4 in open-access papers (continued):
Sharing a sentence is not in itself a finding about the gene and the disease.
neutropenia (22 papers, 2011 to 2025). A decrease in the number of neutrophils found in the blood. "The family shared a heterozygous frameshift variant p.Ser338Phefs*6 in the CXCR4 gene, and three family members had symptoms of cyclic neutropenia, which was the initial diagnosis." (PMID 41383606, 2025). "WHIM mice (a model for the human disease featuring Warts, Hypogammaglobulinemia, Infections, and Myelokathexis) harbor a gain-of-function mutation making CXCR4 hyperactive and are characterized by blood neutropenia due to defective neutrophil trafficking." (PMID 40502695, 2025). "The CXCR4 variant co-segregated with mild neutropenia, recurrent respiratory infections, and cutaneous warts in the paternal lineage." (PMID 40909287, 2025). "The family shared a heterozygous frameshift variant p.Ser338Phefs*6 in the CXCR4 gene, and three family members demonstrated symptoms of cyclic neutropenia, which constituted the initial diagnosis." (PMID 41383606, 2025). "Here, we describe 3 patients presenting neutropenia and myelokathexis, but normal lymphocyte count and immunoglobulin levels, carrying what we believe to be a novel Leu317fsX3 mutation in CXCR4, leading to a complete truncation of its intracellular tail." (PMID 36883568, 2023). "First, genetic knock-in strains of zebrafish or mice harbouring the equivalent of the WHIM-associated CXCR4 mutant phenocopied neutropenia." (PMID 33466410, 2021). "Neutropenia is reversed upon treatment of the WHIM mouse model with the selective CXCR4 antagonist, AMD3100, which causes acute neutrophilia in wild-type mice." (PMID 33466410, 2021). "While G-CSF treatment may also partially ameliorate neutropenia in patients with G6PC3 deficiency by decreasing CXCR4 expression." (PMID 34305938, 2021). "Myelokathexis has been discussed as a mechanism of neutropenia in cases of G6PC3 deficiency associated with increased expression of the bone marrow homing receptor CXCR4 which could expressed selectively on neutrophils and NK cells." (PMID 34305938, 2021). "Blood smear analysis corroborated these results, confirming that the CXCR2 LOF mice exhibited circulating neutropenia, which was reversed by CXCR4 antagonism." (PMID 41451234, 2025). "Our results further support this finding, demonstrating that chronic treatment with a CXCR4 antagonist increased blood neutrophil counts and corrected peripheral blood neutropenia in CXCR2 LOF mice." (PMID 41451234, 2025). "Conversely, patients with loss-of-function (LOF) variants in CXCR2 exhibit many phenotypic traits similar to those seen in individuals with CXCR4 GOF mutations, such as neutropenia, increased susceptibility to infections and myelokathexis." (PMID 41451234, 2025). "However, despite these encouraging findings, there remains a gap in understanding whether CXCR4 antagonists can effectively address peripheral blood neutropenia, abnormal BM neutrophil counts, and infection susceptibility specifically in patients harboring CXCR2 LOF variants." (PMID 41451234, 2025). "Altogether, these results indicate that CXCR4 antagonism corrected peripheral blood neutropenia in CXCR2 LOF mice." (PMID 41451234, 2025). "Cxcr4+/1013 mice exhibited moderate neutropenia; however, this happened in the context of normal neutrophil maturation and was associated with neither accumulation of neutrophils nor increased apoptosis in the BM." (PMID 39588369, 2024). "A heterogeneous genetic landscape was noted in the 7 neutropenia patients with pathogenic variants, two of whom were brothers who shared the same variant: ELANE (n = 4, 66.7%), G6PC3 (n = 1, 16.7%) and CXCR4 (n = 1, 16.7%)." (PMID 35525891, 2022). "We uncovered a key role of neutrophils in the control of infection provided by the CXCR4-gain-of-function mice (Cxcr4+/1013) that display a blood neutropenia as well as an accumulation of skin-infiltrating neutrophils." (PMID 27111140, 2016).
neutropenia (continued). "Future studies will be required to address whether CXCR4 antagonists can correct peripheral blood neutropenia in a Cxcr2-/- mixed BM chimeras and patients with CXCR2 LOF." (PMID 41451234, 2025). "Importantly, CXCR4 antagonist treatment led to a significant increase in absolute neutrophil count and corrected circulating neutropenia in CXCR2 LOF mice." (PMID 41451234, 2025). "To investigate whether CXCR4 antagonism can correct peripheral blood neutropenia, a common clinical phenotype observed in patients with CXCR2 LOF variants, we initially considered using Cxcr2 knockout (Cxcr2-/-) mice." (PMID 41451234, 2025). "Our findings demonstrate that CXCR4 antagonism effectively corrected peripheral blood neutropenia, restored reduced splenic neutrophil counts, normalized mature neutrophil accumulation in BM, and normalized the M/E ratio and MK-like phenotype in BM of CXCR2 LOF mice." (PMID 41451234, 2025). "Notably, the correction of peripheral neutropenia observed in our CXCR2 LOF mice following CXCR4 antagonist treatment suggests a promising alternative for patients with CXCR2 LOF who do not adequately respond to G-CSF." (PMID 41451234, 2025). "The patient (P-08) with a pathogenic CXCR4 mutation (NM_003467.2:c.966_967del, p.(R326fs)) showed permanent neutropenia, several neutropenic fever events with or without infections, inguinal hernia, incomplete cleft lip and serum IgG and IgA deficiencies." (PMID 35525891, 2022). "In addition to these findings, we have studied two patients with GATA2 mutations who presented WS-like features (Mycobacterium avium infection, Warts and Neutropenia) together with an impaired CXCR4 internalization." (PMID 23009155, 2012). "Therefore, the neutropenia that characterizes patients with WHIM is understood to result from the transdominant gain of function and impaired desensitization of the mutant CXCR4 allele." (PMID 33466410, 2021). "CLPB-related neutropenia also accounted for 10% of cases, followed by defects in the TCIRG1 (eight cases), CXCR4 (seven cases), and SRP72 genes (seven cases)." (PMID 41383606, 2025). "The retention of neutrophils in the bone marrow by CXCL12/CXCR4 can be blocked by the CXCR4 antagonist AMD3100 (Plerixafor), which has been used to correct neutropenia in patients." (PMID 26347749, 2015). "While CXCR4 antagonism corrected peripheral blood neutropenia in CXCR2 LOF mice, it did not appear to affect the count of red blood cells or platelets in both CXCR2 LOF and control mice, consistent with a previous report." (PMID 41451234, 2025). "Altogether, these results show that CXCR4 antagonism corrected peripheral blood neutropenia and mobilized functional neutrophils, likely from the BM, without impairing BM granulopoiesis in Cxcr4+/1013 mice." (PMID 39588369, 2024). "This suggests some eventual interplay between CXCR4-dependant signalling and GATA2 that could account for the manifestations of neutropenia and warts of the GATA2 syndrome and beyond, of the more recently described Serine threonine kinase 4 (STK4)-linked syndrome." (PMID 23009155, 2012).
Waldenström’s macroglobulinemia (22 papers, 2014 to 2025). "Previous studies on CXCR4 gain-of-function mutations focused on established Waldenström Macroglobulinemia cell lines, as CXCR4 mutations are present in a third of patients with this disease, thereby limiting conclusions to already transformed cells." (PMID 34363012, 2021). "More recently, mutations in the C-terminus of CXCR4 have been identified in the genomic landscape of patients affected by Waldenstrom’s macroglobulinemia, a rare B cell neoplasm." (PMID 32260318, 2020). "Additionally, responses to ibrutinib were influenced by somatic MYD88 and CXCR4 mutations in patients with Waldenström’s macroglobulinemia." (PMID 34368645, 2021). "Thus, up to 40% of all patients with Waldenström’s macroglobulinemia (WM) carry an activating mutation of CXCR4 that leads to a more aggressive clinical course and inferior outcome upon treatment with the Bruton’s tyrosine kinase inhibitor ibrutinib." (PMID 33669329, 2021). "In Waldenström macroglobulinemia/lymphoplasmacytic lymphoma, a disease in which about 40% of patients have mutations in the CXCR4 gene, preliminary results with non-invasive PET imaging using [68Ga]Pentixafor have demonstrated promising results in both staging and therapy response assessment." (PMID 34885030, 2021). "In addition, about 25% of Waldenstrom macroglobulinemia cases have CXCR4 mutations and are resistant to ibrutinib treatment." (PMID 30100910, 2018). "In addition, they underline that optimizing naturally occurring CXCR4 antagonists can potentially lead to the development of novel therapies in Waldenström’s macroglobulinemia, particular in patients with CXCR4 alterations affected by a more aggressive course of disease." (PMID 33669329, 2021). "Despite recurrent and activating mutations, including MYD88, CXCR4, ARID1A, KMT2D, and CD79B were identified, the genetic basis for Waldenström's Macroglobulinemia (WM) and the risk of progression of IgM MGUS to WM remain to be fully elucidated." (PMID 39711167, 2024). "A recent study has demonstrated that Bcl-2 antagonist ABT-199 triggers apoptosis and augments ibrutinib-mediated cytotoxicity in CXCR4 wild type and CXCR4 WHIM mutated Waldenstrom macroglobulinemia cells." (PMID 27916896, 2016). "Unfortunately, to date the revised International Prognostic Scoring System for Waldenström Macroglobulinemia (IPSSWM) does not include the mutational status of either MYD88 or CXCR4, as it is not routinely performed and is available in only a few patients." (PMID 32260318, 2020). "To date, it has been reported that approximately 30%–40% of patients with Waldenstrom’s macroglobulinemia (WM)—a type of lymphoplasmacytic lymphoma (LPL) exhibiting BM involvement and Immunoglobulin M IgM monoclonal gammopathy—carry mutations in heterozygosis of CXCR4." (PMID 32260318, 2020). "Finally, other CXCR4 antagonists are being evaluated in phase I to phase III clinical trials for treatment of renal cell and hepatocellular carcinoma, Waldenstrom’s macroglobulinemia, and breast cancer." (PMID 36725964, 2023).
osteoarthritis (21 papers, 2008 to 2025). A noninflammatory degenerative joint disease occurring chiefly in older persons, characterized by degeneration of the articular cartilage, hypertrophy of bone at the margins and changes in the synovial membrane. "In this study, we evaluated the effect of the CXCL12/CXCR4 axis on TIMP-3 expression in rats with post-traumatic osteoarthritis (PTOA) and explored the underlying mechanism(s)." (PMID 32038242, 2019). "We evaluated the role of the CXCL12/CXCR4 (C-X-C motif chemokine ligand 12/C-X-C chemokine receptor type 4) axis in aggrecanase-mediated cartilage degradation, and explored the underlying mechanism in a post-traumatic osteoarthritis rat model." (PMID 27690009, 2016). "The C-X-C motif chemokine 12 (CXCL12) and its receptor CXCR4 are pivotal in tissue regeneration and inflammation, yet their role in osteoarthritis (OA) remains ambiguous." (PMID 41331944, 2025). "In conclusion, inhibition of SDF-1α/CXCR4 signaling axis was able to inhibit aggrecanase expression and lessen cartilage degeneration in post-traumatic osteoarthritis rats." (PMID 27690009, 2016). "Those cells promoted meniscus regeneration and ameliorated osteoarthritis through SDF-1/CXCR4-mediated homing in a rat model of meniscus injury." (PMID 28044083, 2016). "Inhibition of the CXCL12/CXCR4 signaling axis slows aggrecanase-mediated catabolic processes and lessens the pathological progress of osteoarthritis." (PMID 27690009, 2016). "Besides, MicroRNA-183 regulates LPS-induced oxidative stress by targeting FN1 and MicroRNA-140-3p can ameliorate the progression of osteoarthritis via targeting CXCR4." (PMID 35281834, 2022). "In addition, blocking the SDF-1/CXCR4 signaling axis has been reported to be able to inhibit cartilage degeneration in osteoarthritis by CXCR4 antagonists." (PMID 32047668, 2020). "However, very few studies have investigated the correlation between miRNAs and the SDF-1/CXCR4 axis in osteoarthritis so far." (PMID 32047668, 2020). "However, there have been very few studies investigating the correlation between miRNAs and the SDF-1/CXCR4 axis in osteoarthritis so far." (PMID 32047668, 2020). "Binding to CXCR4 on BMSCs, SDF-1 can drive cell migration in tissue repair after injury or cartilage repair after osteoarthritis." (PMID 35093078, 2022). "To date, CXCR4, SDF-1 and MCP-1 have been analysed in patients with osteoarthritis (OA) and RA." (PMID 36554439, 2022). "The aim of this study was to determine whether this animal can serve as a more effective osteoarthritis model and explore the role of SDF-1/CXCR4 signaling pathway in the development of Osteoarthritis in animals." (PMID 34649596, 2021). "We evaluated expression of CXCL12/CXCR4 and TIMP-3 in the knee joints of rats with and without osteoarthritis (OA) by immunohistochemistry, immunofluorescence, Western blotting, and enzyme-linked immunosorbent assay (ELISA)." (PMID 32038242, 2019).
renal fibrosis (21 papers, 2014 to 2026). A final common manifestation of a wide variety of chronic kidney diseases characterized by glomerulosclerosis and tubulointerstitial fibrosis. "Our study firstly indicates that CXCR4 promotes senescence‐associated renal fibrosis, which is mediated by β‐catenin activation." (PMID 38213100, 2024). "In CKD, the overexpression of CXCR4 by epithelial cells has been associated with the development of renal fibrosis, making it a potential target for drug development in CKD." (PMID 39253088, 2024). "Our results demonstrated that CXCR4 plays a crucial role in mediating tubular cell senescence and renal fibrosis by inducing β‐catenin‐triggered FAO deficiency." (PMID 38213100, 2024). "Inhibiting CXCR4 has proven effective also in attenuating oxidative stress-induced podocyte injury and renal fibrosis associated with activation of the SDF-1α/CXCR4 axis." (PMID 34884960, 2021). "Although not specifically tested in DM, a selective CXCR4 antagonist AMD3465 decreased mineralocorticoid-dependent renal fibrosis in mice and targeting CXCR4 prevented glomerular injury associated to high podocyte CXCR4 expression in mice." (PMID 28060743, 2017). "CXCR4 also triggered FAO deficiency, cellular senescence and renal fibrosis and was linked to the activation of β‐catenin signalling." (PMID 38213100, 2024). "In summary, our findings first uncovered the key role of CXCR4 in regulating PPARα‐mediated fatty acid oxidation and renal tubular cell senescence‐related renal fibrosis through activating β‐catenin signalling." (PMID 38213100, 2024). "In in vitro study, inhibition of β‐catenin by ICG‐001 largely retarded CXCR4‐induced deficiency of FAO, cellular senescence and renal fibrosis." (PMID 38213100, 2024). "Consistent with our previous study, our results demonstrated that blockade of CXCR4 alleviated renal fibrosis through inhibiting β‐catenin activation." (PMID 38213100, 2024). "In this study, we further confirmed that CXCR4 was predominantly expressed in proximal and distal tubules in renal fibrosis." (PMID 38213100, 2024). "CXCR4 was recently found to be primarily upregulated in tubular epithelial cells in renal fibrosis model and promoted kidney fibrosis by activating JAK/STAT/GSK3β/β‐catenin pathway, as reported by our previous work." (PMID 38213100, 2024). "C‐X‐C motif chemokine receptor 4 (CXCR4), a G‐protein‐coupled seven‐span transmembrane receptor, increases renal fibrosis and plays an important role in tubular cell injury." (PMID 38213100, 2024). "To examine the role of CXCR4 in renal fibrosis, we delivered a flag‐tagged expression plasmid (pFlag‐CXCR4) into normal mice via a hydrodynamic‐based approach." (PMID 38213100, 2024). "CXCR4 promotes tubular cell senescence and renal fibrosis by inducing β‐catenin and inhibiting fatty acid metabolism." (PMID 38213100, 2024). "In a study conducted in 2020 on renal fibrosis, it was found that the binding of CXCL12α to CXCR4 instigates the phosphorylation of JAK2 and JAK3." (PMID 38920657, 2024). "Our previous studies also found that CXCR4 promotes tubular cell injury and renal fibrosis via activating β‐catenin signalling." (PMID 38213100, 2024). "Taken together, our results indicate that CXCR4 is a key mediator in tubular cell senescence and renal fibrosis." (PMID 38213100, 2024). "The results demonstrated that blocking CXCR4 reduced the activity of the p38 MAPK-Kinase, PI3K/AKT/mTOR, and STAT3 signaling pathways implicated in renal fibrosis." (PMID 37893201, 2023). "As i-body AD-114 has been reported to block CXCR4 signaling pathways, we sought to test its efficacy in mitigating renal fibrosis in vivo." (PMID 35015734, 2022). "CXCR4‐induced renal fibrosis was inhibited by treatment with ICG‐001, an inhibitor of β‐catenin signalling." (PMID 32119183, 2020). "To further prove the role of CXCR4 in renal fibrosis, we knocked down renal CXCR4 expression in vivo." (PMID 32119183, 2020).